CMTM2 (CKLF like MARVEL transmembrane domain containing 2)
Synonyms: CKLFSF2; MGC39436; FLJ25732
Tractability: Antibody: UniProt predicts a signal peptide or a membrane-spanning region.
Gene: Protein-coding gene on chromosome 16 (66,579,448 to 66,588,275, forward strand). Ensembl gene ENSG00000140932.
Subcellular location: Membrane
Gene Ontology:
Molecular function: protein binding
Cellular component: membrane
Genetic constraint (gnomAD): Loss-of-function variants: 14 observed, 16.71 expected, observed/expected ratio (o/e) 0.84, 90% interval 0.55 to 1.31. The upper end of that interval is the gene's LOEUF score, 1.31, which puts it in group 5 of 6, group 1 being the genes least tolerant of losing a copy. Missense variants: 276 observed, 332.5 expected, observed/expected ratio (o/e) 0.83, 90% interval 0.75 to 0.92. Synonymous variants: 114 observed, 123.58 expected, observed/expected ratio (o/e) 0.92, 90% interval 0.79 to 1.08.
Homologues: Orthologues: chimpanzee CMTM2 (92% identical), macaque CMTM2 (81% identical), dog CMTM2 (58% identical), pig CMTM2 (51% identical), mouse Cmtm2b (33% identical), rat Cmtm2b (32% identical), mouse Cmtm2a (32% identical), rat Cmtm2a (27% identical), Caenorhabditis elegans F28H1.4 (12% identical), Caenorhabditis elegans F47B3.3 (9% identical). Paralogues in human: CMTM1 (17% identical), CKLF (15% identical), PLP2 (13% identical), CMTM3 (12% identical), CMTM5 (12% identical), CMTM4 (10% identical), CMTM8 (9% identical), MAL (9% identical), CMTM7 (8% identical), MALL (8% identical), PLLP (8% identical), CMTM6 (8% identical), and 2 more.
Diseases named in the same sentence as CMTM2 in open-access papers:
CMTM2 is named in the same sentence as 19 diseases in open-access papers, as found by Europe PMC text mining. Sharing a sentence is not in itself a finding about the gene and the disease. The quoted sentences say what the papers report.
gastric cancer (5 papers, 2020 to 2025). A primary or metastatic malignant neoplasm involving the stomach. "In vitro investigations reveal that SJZD markedly attenuates the proliferation, migration, invasion, and cancer stem cell-like characteristics of gastric cancer cells through the upregulation of CMTM2 expression." (PMID 40103588, 2025). "CMTM2, an immune-related gene within the CMTM family, plays a significant role in tumor progression, and prognosis in gastric cancer." (PMID 40103588, 2025). "CMTM2 has been reported in spermiogenesis, hepatocellular carcinoma, HBV-related disorders, and gastric cancer." (PMID 37545529, 2023). "Moreover, a significant novel mutation at CMTM2 was correlated with lymph node metastasis in diffuse-type gastric cancer (DGC), and CMTM2 overexpression significantly restrained cell proliferation in GC cells." (PMID 33033510, 2020).
hepatocellular carcinoma (3 papers, 2020 to 2023). A malignant tumor that arises from hepatocytes. "CMTM2 is an immune-related gene belonging to CMTM2 family and closely related to tumor progression, recurrence, and prognosis in lung cancer, hepatocellular cancer, and GC." (PMID 35873650, 2022). "Next, we show that negative expression of CMTM2 may participate in the progression of hepatocellular carcinoma." (PMID 33101541, 2020).
Sézary syndrome (3 papers, 2020 to 2021). "The hypermethylation of CMTM2 promoter with concomitant transcriptional downregulation might perform tumor suppressive functions in Sézary syndrome." (PMID 33101541, 2020). "CMTM2 was found to be expressed at significantly lower level in Sézary syndrome (Sz), an aggressive type of cutaneous T‐cell lymphoma, than in benign T‐cell samples, and hypermethylation of CMTM2 promoter can distinguish Sz from erythroderma secondary to inflammatory skin diseases." (PMID 32688456, 2020).
liver cancer (2 papers, 2020 to 2022). An epithelial or non-epithelial malignant neoplasm that arises from the liver. "Previous studies indicated that CMTM2 is downregulated in liver cancer tissues, which is related to the outcome of liver cancer patients." (PMID 35252165, 2022). "In the present study, restoring CMTM2 expression not only inhibited liver cancer cell growth via G2/M phase accumulation without inducing apoptosis, but also suppressed cell metastasis and invasion in vitro." (PMID 33101541, 2020).
lung adenocarcinoma (2 papers, 2020 to 2022). A carcinoma that arises from the lung and is characterized by the presence of malignant glandular epithelial cells. "Immunohistochemistry quantification results confirmed that markers are weakly expressed in human lung adenocarcinoma, and CMTM2 decreased tumor growth of mouse Lewis lung carcinoma in vivo." (PMID 32688456, 2020). "We identified three novel methylation markers in lung adenocarcinoma including cg08032924, cg14823851, and cg19161124, mapping to CMTM2, TBX4, and DPP6, respectively." (PMID 32688456, 2020). "We found CD1A|CXCL13, CD1A|S100A7L2, IFNA7|CMTM2, IFNA7|CSF3, CAMP|TFR2, this 5‐IRGPs were strongly associated with the prognosis of patients, all of which were protective factors for the prognosis of lung adenocarcinoma." (PMID 35246970, 2022).
antiphospholipid syndrome (1 paper, 2023). A disorder caused by the presence of autoantibodies directed against phospholipids, causing a hypercoaguable state, which may result in blood clots, stroke, heart attack, and in women, significant pregnancy-related complications, including miscarriage and still birth. "CMTM2, a member of the CMTM family and characteristic biomarker of SCI AIS D, is widely expressed in the immune system, is involved in T-cell and B-cell activation and is closely related to autoimmune diseases such as antiphospholipid syndrome." (PMID 37063890, 2023).
Lewis lung carcinoma (1 paper, 2020). "To elucidate the role of Cmtm2 in LUAD, we examined the effects of Cmtm2 on mouse Lewis lung carcinoma (LLC) in vivo." (PMID 32688456, 2020).
liver diseases (1 paper, 2020). "In this report, we aim to explore the changes of serum CMTM2 in patients with HBV-related liver diseases and get a better insight into the association between serum levels of CMTM2 and HBV-related complications." (PMID 33101541, 2020). "The serum concentration of CMTM2 in patients with HBV-related liver diseases was significantly lower than those of healthy individuals." (PMID 33101541, 2020). "In general, our findings strongly indicate that the patients with HBV-related liver diseases showed significantly decreased serum CMTM2 levels than the healthy group." (PMID 33101541, 2020). "To identify whether serum CMTM2 could be abnormally altered in patients with HBV-related liver diseases, we analyzed CMTM2 levels in four groups, including CHB, HBLC, HCC and healthy individuals." (PMID 33101541, 2020). "However, until now, whether or not CMTM2 is involved in HBV-related liver disorders remains to be elucidated." (PMID 33101541, 2020). "Therefore, the serum CMTM2 levels of HBV-related liver disorders may be related to HBV replication, but not related to the degree of inflammatory injury." (PMID 33101541, 2020).
male infertility (1 paper, 2023). The inability of the male to effect fertilization of an ovum after a specified period of unprotected intercourse. "In this study, an Ampiseq targeted NGS panel and Illumina TruSeq WES were both used to pinpoint six specific genes (KIF6, DRC7, STPG2, SPATA16, CFTR, CMTM2) that play a role in MT association and spermiogenesis, which are crucial factors in understanding the causes of male infertility." (PMID 37895049, 2023).
ovarian carcinoma (1 paper, 2022). A malignant neoplasm originating from the surface ovarian epithelium. "In addition, CMTM2/3/5 and progression-free survival of ovarian cancer patients were significantly associated." (PMID 36110202, 2022).
virus infection (1 paper, 2020). "Recently, CMTM2 was discovered to play a pivotal role in some virus infection." (PMID 33101541, 2020).
tumor (7 papers, 2020 to 2024). "Consequently, CMTM2+ neutrophils could be deemed as tumour‐associated neutrophils (TANs)." (PMID 39422697, 2024). "Then, we verified that the expression of CMTM2 mRNA was elevated by SJZ treatment in both tumor tissues and GC SGC7901 cells by qRT-PCR." (PMID 35873650, 2022). "It is noticeable that the elevation of Cmtm2 significantly suppressed the subcutaneous tumor growth compared with the control group even in the early stage." (PMID 32688456, 2020). "As a transcription factor, CMTM2 expression was downmodulated in HCC tissues, and low CMTM2 expression was associated with the poor prognosis of HCC patients, suggesting a potential tumor suppressor role of CMTM2 in HCC progression." (PMID 33033510, 2020). "Intriguingly, we found that C1Q+ TAMs may recruit CMTM2+ TANs via the chemokine pathway, potentially promoting tumour progression synergistically." (PMID 39422697, 2024). "Furthermore, we suggested an important role for LINC01391 in aerobic glycolysis and tumor progression of GC via competitively binding and repressing miR-12116 to facilitate CMTM2 expression in GC." (PMID 33033510, 2020). "Moreover, the expression level of CMTM2 in SACC patients with tumor recurrence and perineural invasion is low too." (PMID 33282744, 2020). "In summary, CMTM2 plays tumor suppressive role and the expression level in tumor tissues could be a predictor of HCC, which could further guide postoperative treatment." (PMID 33282744, 2020). "Moreover, we demonstrated that Cmtm2 could suppress the tumor growth of LUAD in vivo." (PMID 32688456, 2020).
cancer (4 papers, 2019 to 2024). A tumor composed of atypical neoplastic, often pleomorphic cells that invade other tissues. "In the present study, we found that SJZ treatment elevated CMTM2 mRNA and protein expression levels, and suppressed the proliferation, migration, invasion, and cancer stem cell-like properties of GC cells." (PMID 35873650, 2022). "CMTM2 knockdown antagonized the effects of SJZ on the cancer stem cell-like properties of SGC7901 cells." (PMID 35873650, 2022). "To further investigate the relationship between cancer stem cell-like properties and CMTM2, we detected the expression of stem cell markers SOX2, NANOG, and CD44 in SGC7901 cells using qRT-PCR and western blotting." (PMID 35873650, 2022). "Thus, SJZ effectively suppressed the proliferation, migration, invasion, and cancer stem cell-like properties of GC cells in vitro by upregulating CMTM2 expression." (PMID 35873650, 2022). "We speculated that SJZ suppressed the proliferation, migration, invasion, and cancer stem cell-like properties of GC cells in vitro may be through the activation of CMTM2." (PMID 35873650, 2022). "Given the putative pivotal roles of C1Q+ TAMs, CMTM2+ TANs, and MUC1+ cancer cells in mediating treatment resistance, the DREIMT tool was used to prioritize the potential drugs targeting them." (PMID 39422697, 2024). "In addition, knockdown of CMTM2 could antagonize the effects of SJZ on SGC7901 cells' expression of SOX2, NANOG, and CD44 and their cancer stem cell-like properties." (PMID 35873650, 2022).
CMTM2 also shares sentences with these, for which no sentence is quoted: lung carcinoma (2 papers); Alzheimer disease (1); autoimmune disease (1); breast carcinoma (1); erythroderma (1); inflammatory skin disease (1).